Y_RNA (Y RNA )
Gene: Miscellaneous RNA gene on chromosome 14 (63,621,760 to 63,621,871, forward strand). Ensembl gene ENSG00000206822.
Homologues: Orthologues: chimpanzee Y_RNA (99% identical), macaque Y_RNA (95% identical). Paralogues in human: Y_RNA (88% identical), Y_RNA (87% identical), RNY1P5 (85% identical), Y_RNA (85% identical), Y_RNA (83% identical), Y_RNA (82% identical), Y_RNA (81% identical), RNY1 (80% identical), Y_RNA (80% identical), Y_RNA (79% identical), RNY1P1 (79% identical), RNY1P16 (79% identical), and 96 more.